FCER1G (Fc epsilon receptor Ig)
Description:
Adapter protein containing an immunoreceptor tyrosine-based activation motif (ITAM) that transduces activation signals from various immunoreceptors. As a component of the high-affinity immunoglobulin E (IgE) receptor, mediates allergic inflammatory signaling in mast cells. As a constitutive component of interleukin-3 receptor complex, selectively mediates interleukin 4/IL4 production by basophils, priming T-cells toward effector T-helper 2 subset. Associates with pattern recognition receptors CLEC4D and CLEC4E to form a functional signaling complex in myeloid cells. Binding of mycobacterial trehalose 6,6'-dimycolate (TDM) to this receptor complex leads to phosphorylation of ITAM, triggering activation of SYK, CARD9 and NF-kappa-B, consequently driving maturation of antigen-presenting cells and shaping antigen-specific priming of T-cells toward effector T-helper 1 and T-helper 17 cell subtypes. May function cooperatively with other activating receptors. Functionally linked to integrin beta-2/ITGB2-mediated neutrophil activation. Also involved in integrin alpha-2/ITGA2-mediated platelet activation.
Synonyms: FcepsilonRIgamma; FCRG
Tractability: Small molecule: a structure with a bound ligand is known. Antibody: UniProt places it where antibodies can reach, with high confidence; its Gene Ontology location is reachable by antibodies, with high confidence; UniProt predicts a signal peptide or a membrane-spanning region. PROTAC: ubiquitination databases record sites on it; its protein half-life has been measured.
Safety:
Unwanted effects reported when the protein is acted on. In parentheses: how it was acted on, where the effect was seen, and who reports it.
aspirin sensitivity (source: ClinPGx)
Gene: Protein-coding gene on chromosome 1 (161,215,234 to 161,220,699, forward strand). Ensembl gene ENSG00000158869.
Subcellular location: Cell membrane
Pathways (Reactome):
Immune System: Dectin-2 family; FCERI mediated Ca+2 mobilization; FCERI mediated MAPK activation; FCERI mediated NF-kB activation; Fc epsilon receptor (FCERI) signaling; Neutrophil degranulation; Role of LAT2/NTAL/LAB on calcium mobilization
Hemostasis: Cell surface interactions at the vascular wall; GPVI-mediated activation cascade; Platelet Adhesion to exposed collagen
Gene Ontology:
Molecular function: identical protein binding; protein binding; protein homodimerization activity; IgE receptor activity; IgE binding; IgG binding; transmembrane signaling receptor activity
Biological process: Fc-epsilon receptor signaling pathway; cellular response to low-density lipoprotein particle stimulus; Fc-gamma receptor signaling pathway; immunoglobulin mediated immune response; innate immune response; interleukin-3-mediated signaling pathway; positive regulation of interleukin-4 production; receptor internalization; cell surface receptor signaling pathway; integrin-mediated signaling pathway; neutrophil activation involved in immune response; regulation of platelet activation; serotonin secretion by platelet
Cellular component: cell surface; Fc-gamma receptor III complex; plasma membrane; external side of plasma membrane; Fc-epsilon receptor I complex; ficolin-1-rich granule membrane; tertiary granule membrane; membrane; plasma membrane protein complex
Genetic constraint (gnomAD): Loss-of-function variants: 7 observed, 18.83 expected, observed/expected ratio (o/e) 0.37, 90% interval 0.21 to 0.7. The upper end of that interval is the gene's LOEUF score, 0.7, which puts it in group 2 of 6, group 1 being the genes least tolerant of losing a copy. Missense variants: 87 observed, 102.58 expected, observed/expected ratio (o/e) 0.85, 90% interval 0.71 to 1.01. Synonymous variants: 35 observed, 41.2 expected, observed/expected ratio (o/e) 0.85, 90% interval 0.65 to 1.13.
Homologues: Orthologues: macaque FCER1G (99% identical), pig FCER1G (98% identical), dog FCER1G (94% identical), guinea pig FCER1G (93% identical), rat Fcer1g (91% identical), mouse Fcer1g (88% identical), rabbit FCER1G (88% identical), chimpanzee FCER1G (79% identical), zebrafish cd247l (34% identical).
Diseases named in the same sentence as FCER1G in open-access papers:
FCER1G is named in the same sentence as 116 diseases in open-access papers, as found by Europe PMC text mining. Sharing a sentence is not in itself a finding about the gene and the disease. The quoted sentences say what the papers report.
clear cell renal cell carcinoma (14 papers, 2019 to 2024). "FCER1G was implicated in the progression of several cancers, such as squamous cell carcinoma, multiple myeloma, and clear cell renal cell carcinoma." (PMID 36778919, 2023). "An association between FCER1G gene expression and clear cell renal cell carcinoma (ccRCC) was also noted." (PMID 36012903, 2022). "FCER1G is associated with the progression of clear cell renal cell carcinoma (ccRCC) and may improve prognosis by affecting the immune-related pathways." (PMID 31956364, 2020). "Additionally, FCER1G is associated with the progression of clear-cell renal cell carcinoma and may improve prognosis by affecting immune-related pathways." (PMID 32894197, 2020). "It has been illustrated that FCER1G participated in various kidney diseases, such as diabetic kidney disease and clear cell renal cell carcinoma." (PMID 35836957, 2022). "As indicated, Fcer1g is related to various kidney diseases, e.g., clear cell renal cell carcinoma and diabetic kidney disease." (PMID 36523757, 2022). "Furthermore, FCER1G is the essential molecule involved in the progression of many kinds of tumors, such as clear cell renal cell carcinoma (ccRCC), meningioma, acute myeloid leukemia (AML), and childhood leukemia." (PMID 40626122, 2024). "FCER1G was functionally joined to mediate neutrophil activation and was additionally concerned in platelet activation, and improved prognosis by affecting the immune-related pathways in the progression of clear cell renal cell carcinoma (ccRCC)." (PMID 35246248, 2022). "FCER1G takes part in promoting squamous carcinogenesis (SCC) progression, and predicts poor prognosis in gliomas and clear cell renal cell carcinomas (RCC)." (PMID 36900319, 2023). "Furthermore, FCER1G and TYROBP have been identified as two of three hub genes in a protein-protein interaction network positively correlated with the progression of clear cell renal cell carcinoma." (PMID 31139325, 2019). "Fc Fragment of IgE Receptor Ig (FCER1G) mediates allergic inflammatory signaling as a component of the high-affinity immunoglobulin E (IgE) receptor, and it is a critical molecule in developing eczema, clear cell renal cell carcinoma, meningioma and childhood leukemia." (PMID 35711924, 2022).
viral infection (11 papers, 2010 to 2026). "LILRA4 is a coreceptor that controls innate immune responses generated through FCER1G in viral infection and acts as a negative regulator of TLR7 and TLR9 signaling cascades." (PMID 37435086, 2023). "Moreover, FCER1G acts as a critical regulator within the natural killer (NK) cell–CD8+ T-cell axis during chronic viral infection, where its absence enhances CD8+ T-cell responses and accelerates viral control." (PMID 41602333, 2026). "To address the question of whether the lack of FcRγ indeed limits virus-specific CD8+ T-cell functions during chronic viral infection, we infected adult Fcer1g+/+ and Fcer1g–/– mice with LCMV-Docile and determined CD8+ T-cell responses." (PMID 31220194, 2019). "Following viral infection, a significant increase in the frequency of microglia expressing iNOS was found in FcgR2b KO mice (8.07%) when compared with either WT (3.68%) (***p < 0.001) or Fcer1g KO mice (3.08%) (***p < 0.001) at 14 dpi." (PMID 28165503, 2017).
allergic reactions (10 papers, 2015 to 2024). "FCER1G, which encodes the Fc fragment of the IgE receptor Ig, is involved in allergic reactions." (PMID 32903590, 2020). "FCER1G, also referred to as Fc receptor-gamma (FcRγ), plays a significant role in allergic reactions." (PMID 39062086, 2024). "FCGR2B and FCER1G are immunoglobulin fragments that regulate the immune response, and increase the likelihood of obese patients developing allergic diseases." (PMID 34093637, 2021). "The specific binding of lgE and FCER1G leads to the release of many mediators that can induce allergic reactions." (PMID 34504502, 2021). "Up-regulated FCER1G directs mast cell and coupling allergens to suppress inflammatory and immediate hypersensitivity responses in immunity to parasites and in allergic diseases." (PMID 25903558, 2015). "Also, the high affinity IgE receptor (Fcer1g), a key mediator of allergic reactions, is strongly induced." (PMID 36386828, 2022). "Fcer1g, a high‐affinity IgE receptor, is a key molecule involved in allergic reactions." (PMID 37786556, 2021). "The high affinity Ig E receptor, FCER1G, is a key molecule involved in allergic reactions." (PMID 34257539, 2021). "FCER1G is the primary component of the immunoglobulin E (IgE) receptor and interleukin 3 (IL3) receptor complex, making it an essential molecule in allergic reactions." (PMID 38783198, 2024).
Arthritis (10 papers, 2008 to 2020). Inflammation of a joint. "Interestingly, Fcer1g, Fcgr3 are both show a correlation with gene expression of Il1rn as well as differential expression between spontaneous arthritis mice and healthy BALB/c mice." (PMID 25488730, 2014). "Our current analysis indicates that the other three genes, Fcer1g, Fcgr3, and Kmo, were not differentially regulated in congenic strains compared to BALB/c-/- that is susceptible to spontaneous arthritis." (PMID 27480124, 2016).
COVID-19 (10 papers, 2021 to 2025). A disease caused by infection with severe acute respiratory syndrome coronavirus 2. "Recent research has demonstrated the involvement of FCER1G in the pathogenesis of various diseases, including glioma, diabetic kidney disease, endometrial cancer, COVID-19, and osteosarcoma." (PMID 39062086, 2024). "Seven common key genes were found in these four hub gene sets, including FCER1G, ITGAM, LCP2, LILRB2, MNDA, SPI1, and TYROBP, which were considered core targets of IC and COVID-19." (PMID 38267482, 2024). "In general, FCER1g, ICAM1, LAT, LCN2, and PLAU may be the main immune genes that are regulated by COVID-19 to induce olf and neurological dysfunction." (PMID 34504502, 2021).
asthma (8 papers, 2016 to 2025). "State 1 was defined as asthma-related eosinophils predominantly found in the asthma model, including the following genes: H2Aa, Ms4a2, Fcer1g, and Rpl10." (PMID 37816708, 2023).
Sepsis (8 papers, 2015 to 2026). Sepsis is defined as life-threatening organ dysfunction caused by a dysregulated host response to infection. "In conclusion, our study illuminates the complex genetic landscape of sepsis, with a particular focus on the roles of FCER1G and FYN." (PMID 39430765, 2024). "Bioinformatics analysis underscored the pivotal role of activated hemocytes in diagnosing pediatric sepsis, with SPI1, TYROBP, and FCER1G co‐expression influencing the disease's pathophysiology by modulating neutrophil and platelet activity." (PMID 40626122, 2024). "Patients with sepsis exhibit higher expression of FCER1G and lower expression of FYN, suggesting a complex interplay between these genes in the immune response during sepsis." (PMID 39430765, 2024). "Our study’s insights into FCER1G and FYN enhance our understanding of sepsis and open new avenues for diagnostics and therapeutics." (PMID 39430765, 2024). "Additionally, experimental studies are needed to fully understand the mechanisms by which FCER1G and FYN influence sepsis progression." (PMID 39430765, 2024).
atherosclerosis (5 papers, 2023 to 2025). A disease characterized by the build-up of fatty material and calcium deposition in the arterial wall resulting in partial or complete occlusion of the arterial lumen. "The expression of the genes CYBB, FCER1G, TYROBP, IL10RA, and CSF1R is increased in both ANCA-associated vasculitis and atherosclerosis." (PMID 39702436, 2024). "According to the findings of our research, the genes CYBB, FCER1G, TYROBP, IL10RA, and CSF1R could represent relevant targets for the study and development of therapeutic strategies aimed at ANCA-associated vasculitis and atherosclerosis." (PMID 39702436, 2024). "Other genes, such as FCER1G, might influence the formation of atherosclerotic plaques through antibody responses, while CD86 might affect atherosclerosis by mediating T cells/DCs activation." (PMID 41348730, 2025).
autoimmune disease (5 papers, 2018 to 2022). A disorder resulting from loss of function or tissue destruction of an organ or multiple organs, arising from humoral or cellular immune responses of the individual to their own tissue constituents. "FCER1G may interact with members of the Dectin-2 family which was identified as a locus associated with various autoimmune disorders, including systemic lupus erythematosus and RA." (PMID 36012903, 2022).
glioma (5 papers, 2020 to 2025). A benign or malignant brain and spinal cord tumor that arises from glial cells (astrocytes, oligodendrocytes, ependymal cells). "Then, we explore the underlying molecular mechanisms of FCER1G in tumor progression and potential correlation between FCER1G expression and immune cell activation and response to immunotherapy in patients with glioma." (PMID 33579299, 2021). "Furthermore, we illustrated gene FCER1G as a novel diagnostic and therapeutic target for the first time, which stratified glioma cases into high and low FCER1G expression subgroups that demonstrated with distinct clinical outcomes." (PMID 33579299, 2021). "To better understand the role of expression of FCER1G in patients with glioma, we analyzed the CGGA dataset with clinical data of 1013 glioma patients." (PMID 33579299, 2021). "To explore the expression levels of FCER1G mRNA in different stages of gliomas, we used six datasets to analyze FCER1G expression levels." (PMID 33579299, 2021). "Through high-throughput expression profiling, WGCNA, lasso, and multivariate Cox analysis, we acquired eight genes (HCK, HAVCR2, CD37, LPAR5, NAGA, C1QC, FCER1G and AIF1) to construct the MRGs signature in Grade II/III glioma patients." (PMID 33186124, 2020).
meningioma (5 papers, 2020 to 2024). A generally slow growing tumor attached to the dura mater. "Previous studies have established FCER1G as a gene linked to innate immunity and its involvement in the malignant progression of conditions such as eczema, meningioma, PTC and childhood leukemia." (PMID 38971817, 2024). "FCER1G expression has been studied and described in various diseases, including squamous cell carcinoma, eczema, meningioma, leukemia, glioma, kidney disease, and even in acute myocardial infarction." (PMID 36012903, 2022). "Previous studies have shown that FCER1G is involved in the development of innate immunity and may be responsible for the development of eczema, meningioma and childhood leukemia." (PMID 36012903, 2022). "Previous studies have shown that FCER1G is an innate immunity gene and may be involved in the development of eczema, meningioma and childhood leukemia 12-14." (PMID 31956364, 2020).
osteosarcoma (5 papers, 2021 to 2025). A usually aggressive malignant bone-forming mesenchymal neoplasm, predominantly affecting adolescents and young adults. "The upregulation of immune-related genes such as CD86, FCER1G, and ITGAM suggests involvement of immune activation and inflammatory signaling within the osteosarcoma microenvironment." (PMID 40895569, 2025). "used integrative analysis of single-cell and bulk transcriptome data to discover neutrophil-related genes in osteosarcoma, such as C3AR1 and FCER1G." (PMID 39324133, 2024). "C3AR1 and FCER1G were highly regulated in the osteosarcoma mice induced by K7M2, and these two genes were proven to have significant prognostic value in osteosarcoma." (PMID 39582869, 2024).
Alzheimer disease (4 papers, 2011 to 2024). A progressive, neurodegenerative disease characterized by loss of function and death of nerve cells in several areas of the brain leading to loss of cognitive function such as memory and language. "The lysosomal cysteine proteinase Ctss and the high affinity IgE receptor gamma subunit Fcer1g, which were both downregulated in the current study, are associated with Alzheimer's disease (AD), and in particular, Fcer1g is considered as a risk factor for AD." (PMID 30013462, 2018). "RNA sequencing and genetic data support spleen tyrosine kinase (SYK) and high affinity immunoglobulin epsilon receptor subunit gamma (FCER1G) as putative targets to be modulated for Alzheimer’s disease (AD) therapy." (PMID 38359047, 2024). "Tyrobp and Fcer1g was found to be differentially expressed in Alzheimer’s disease (AD) mouse models that demonstrated strong correlation between cortical Aβ amyloidosis and the neuroinflammatory response." (PMID 32322218, 2020).
HCMV infection (4 papers, 2017 to 2025). "The adaptive-like NK cells featured high expression of CD3E, LAG3, and IL-32 with no expression of FCER1G and TCRs, consistent with published scRNA-seq data (except for low expression of KLRC2/NKG2C, the canonical markers for adaptive NK cells after human cytomegalovirus (HCMV) infection) 21,22." (PMID 40394087, 2025).
lupus nephritis (4 papers, 2021 to 2022). Glomerulonephritis in the context of systemic lupus erythematosus. "Recently FCER1G was identified as a marker of inflammatory dendritic cells and abundantly expressed in the periglomerular region of the lupus nephritis kidney." (PMID 35836957, 2022). "Recently, Fcer1g has been identified to be a biomarker of inflammatory dendritic cells as it is excessively expressed in the periglomerular region of the lupus nephritis kidney." (PMID 36523757, 2022).
malaria (4 papers, 2020 to 2025). Malaria is a serious and sometimes fatal disease caused by a parasite that commonly infects a certain type of mosquito which feeds on humans. "We and others have found that individuals with malaria experience have an adaptive NK cell subset that lacks Fcer1g and PLZF and correlates with reduced parasitemia and protection from malaria symptoms." (PMID 40337867, 2025). "However, consistent with transcriptional upregulation of CD64/FcγRI genes FCGR1A and FCER1G (common FcRγ chain) in children, CD64/FcγRI cell surface expression on monocyte subsets was increased in both children and adults during malaria." (PMID 32566226, 2020).
acute myeloid leukemia (3 papers, 2020 to 2024). Acute myeloid leukemia (AML) is a group of neoplasms arising from precursor cells committed to the myeloid cell-line differentiation. "In this study, we identified SE-associated genes by integrating cell-specific SEs with RNA-seq data and found six genes (CAPG, CD207, GPR132, SLC7A11, HIPK3 and FCER1G) that are correlated with poor prognosis in acute myeloid leukemia (AML) patients according to the TCGA-LAML database." (PMID 37296281, 2023).
leukemia (3 papers, 2020 to 2025). A malignant (clonal) hematologic disorder, involving hematopoietic stem cells and characterized by the presence of primitive or atypical myeloid or lymphoid cells in the bone marrow and the blood. "FCER1G plays a tumor-promoting role in various tumors such as leukemia and solid tumors of the renal and Meninges." (PMID 33186124, 2020).